ENSG00000288623 (novel protein)
Synonyms: LOC128071547
Gene: Protein-coding gene on chromosome 12 (120,534,697 to 120,534,957, forward strand). Ensembl gene ENSG00000288623.
Genetic constraint (gnomAD): Loss-of-function variants: 8 observed, 5.04 expected, observed/expected ratio (o/e) 1.59, 90% interval 0.86 to 1.94. That is too few expected variants to judge how well the gene tolerates losing a copy. Missense variants: 126 observed, 102.93 expected, observed/expected ratio (o/e) 1.22, 90% interval 1.06 to 1.42. Synonymous variants: 72 observed, 50.9 expected, observed/expected ratio (o/e) 1.41, 90% interval 1.17 to 1.72.